BAP1 (BRCA1 associated deubiquitinase 1)
Diseases named in the same sentence as BAP1 in open-access papers (continued):
Sharing a sentence is not in itself a finding about the gene and the disease.
cancer (continued). "Here we performed integrated multi-omic analyses using data from The Cancer Genome Atlas (TCGA) for 33 cancer types and over 10,000 individuals to identify alterations leading to BAP1 disruption." (PMID 38045292, 2024). "Here, we account for these additional types of alterations across a broader set of cancer types represented in TCGA to better characterize functional consequences of BAP1 alteration in cancer." (PMID 39554490, 2024). "We validated our score using data from BAP1 knockout cancer organoid models that had lower BAP1 activity scores compared to parental organoids." (PMID 39554490, 2024). "Among the proteins capable of redesigning cancer cell signalling, greater consideration for its prominence in PMe was gained by the BRCA1‐associated protein 1 (BAP1)." (PMID 38459714, 2024). "In a previous report, BAP1 increased cell growth, whereas abnormal activity of BAP1 inhibited cell growth in several cancers." (PMID 38708315, 2024). "None of the patients displayed pathogenic or likely pathogenic variants in the BAP1 and MBD4 genes or in other well-established cancer-predisposing genes." (PMID 38892746, 2024). "BAP1 has become a research hotspot in the field of cancer because of its ability to reduce histone 2 A ubiquitination (H2Aub) on the downstream protein chromatin." (PMID 38816686, 2024). "All five genes (BAP1, FANCA, RET, FH, and RAD51C) are well-known cancer predisposing genes with incomplete penetrance and variability of expression." (PMID 38700789, 2024). "As core components of the PR-DUB complex, ASXL1/2/3 and BAP1 regulate epigenetic modification of histones in various tissues and in the context of human cancer." (PMID 38366571, 2024). "PPI of BAP1 with BRCA1 was central to understanding the role of BAP1 in growth-control pathways and cancer; BAP1 was suggested to play a role in BRCA1 stabilisation." (PMID 39516360, 2024). "In cancer cells, BRCA1-associated protein 1 (BAP1) removes monoubiquitin from ubiquitinated H2A at lysine 119 (H2Aub) on the SLC7A11 promoter, thereby suppressing its expression in cells treated with erastin and activating ATF4." (PMID 39595619, 2024). "Here we performed integrated multi-omics analyses using data from The Cancer Genome Atlas for 33 cancer types and over 10 000 individuals to identify alterations leading to BAP1 disruption." (PMID 39554490, 2024). "We observed that simultaneously inhibiting these two proteins harmed cancer cells (BAP1-positive and BAP1-negative cell lines) concerning all tested parameters, which was not the case when the inhibitors were applied separately." (PMID 39195238, 2024). "Here, we report 9 out of 24 patients with non-contributory family history, harboring germline heterozygous deleterious mutation in well-known cancer predisposing genes (CHEK2, RAD51C, BRCA2, FANCA, RET, FH, and BAP1)." (PMID 38700789, 2024). "Decreased concentrations of the functional protein driven on by germline BAP1 alterations promote retention of genomic alterations and finally cancer." (PMID 37469419, 2023). "Specifically, BAP1 suppresses genome instability via its DNA repair activity and eliminates cancer-prone cells that exhibit genome instability by promoting apoptosis." (PMID 37009801, 2023). "The most frequent mutations in a large panel of 1123 cancer-related genes in the overall population of RCC patients were VHL (51%), PBRM1 (35%), BAP1 (16%), KMT2D (15%), PTPRD (15%), and SETD2 (15%)." (PMID 37427096, 2023).
cancer (continued). "Interesting candidate are the ubiquitin C-terminal hydrolases (UCHs: UCH-L1, UCH-L3, UCH-L5, and BAP1), a subfamily of deubiquitinating enzymes, which we have recently shown to be involved in both cancer and NDD." (PMID 36923654, 2023). "BAP1 is a multifunction suppressor of cancer that influences the immune system, cell cycle control, DNA damage response via its connection with BRCA1, chromatin remodeling, and DNA damage response." (PMID 37770494, 2023). "BAP1 plays roles in many cancer-related cellular functions, including cell proliferation, cell death, and nuclear processes crucial for genome stability, such as DNA repair and replication." (PMID 36754982, 2023). "Several pioneering studies using advanced sequencing technologies have revealed a BAP1 link to human cancer." (PMID 37009801, 2023). "In some cancers, high ASS1 is associated with poor prognosis; however, like BAP1 loss, elevated ASS1 is associated with better OS in patients with MPM." (PMID 36669126, 2023). "We have found that a mimicked BAP1 cancer missense mutation (UBH-4 A87D; BAP1 A95D) resembles the phenotypes of ubh-4 deletion mutants." (PMID 36980270, 2023). "A reduction in BAP1 protein levels supports the reprogramming of cancer cell metabolism, with a switch from TCA/OXPHOS to aerobic glycolysis." (PMID 37626858, 2023). "Further studies are clearly required to substantiate the applicability of PARP inhibition to a synthetic lethality-based treatment of BAP1-related cancers." (PMID 37009801, 2023). "Resolving all these compelling issues will provide a better picture of how BAP1 prevents cancer as a guardian of the genome." (PMID 37009801, 2023). "The largest reported study of BAP1-TPDS carriers (n = 181 families) suggests that lifetime cancer risks were reported to be different for truncating compared to missense variants." (PMID 37607989, 2023). "Studies in which advanced sequencing technologies were used have uncovered a link between BAP1 and human cancer." (PMID 37009801, 2023). "PRCC also displays mutations in previously studied cancer-related pathways; these include NF2 (Hippo pathway), SMARCB1 and PBRM1 (SWI/SNF complex), and chromatin modifier pathways (SETD2, KDM6A, and BAP1)." (PMID 38162463, 2023). "Recently, BAP1 depletion has proved a nearly 100% predictive indicator of cancer in mesothelial differentiation." (PMID 37469419, 2023). "It has been demonstrated the role of BAP1 in attenuating cancer development by provoking the ferroptosis event via solute carrier family 7-member 11 (SLC7A11) inhibition." (PMID 35205167, 2022). "Further research on the effect of hypoxia-induced HIF-1α stabilization on BAP1 would shed light on new molecular mechanisms of various events including cell death in cancer." (PMID 35205167, 2022). "Using integrated analysis, the relationship between BAP1 and multiple immune checkpoints in pan-cancer was revealed." (PMID 36003792, 2022). "The BAP1 gene is commonly deleted or altered in human cancer, including lung cancer, breast cancer, as well as renal cancer." (PMID 35408533, 2022). "Basal cell carcinoma, cholangiocarcinoma, and meningioma are also considered likely BAP1 cancer syndrome-related cancers." (PMID 35381901, 2022). "Therapeutic approaches targeting the role of BAP1 in cancer are currently under investigation, with on-going clinical studies assessing the effectiveness of PARP, EZH2 and HDAC inhibitors." (PMID 35381901, 2022). "It has been known that the activity of BAP1 is critical for the maintenance of the protein stability of the additional sex combs-like protein ASXL1-3, including CTD-truncated ASXL1 variant in cancer." (PMID 35194152, 2022).
cancer (continued). "In cancer cells, BAP1 inactivation leads to the overexpression of SLC7A11, the suppression of ferroptosis, and the formation of tumors." (PMID 35408533, 2022). "PTEN, ATM, and BAP1 were the most frequently affected genes pan-cancer (34%, 7%, and 4% of all H1b cases)." (PMID 35681079, 2022). "The patient was enrolled in a cancer surveillance program, in accordance with current recommendations for patients with BAP1 cancer syndrome." (PMID 35381901, 2022). "BAP1 promotes double-strand DNA repair by homologous recombination, a key process to reduce genetic damage and prevent cancer." (PMID 34976173, 2022). "Currently, the relationship between BAP1 and tumors is receiving increasing attention, and its structural stability and functional integrity are of great importance to the performance of cancer suppression." (PMID 36003792, 2022). "More importantly, we found that BAP1 protein level positively correlates with PTEN in a substantial fraction of human cancers." (PMID 33155366, 2021). "Personalised treatments are lacking for MPM5, however recent insights into the inter-patient genomic heterogeneity of this cancer have revealed frequent somatic alterations involving the cancer genes BAP1, NF2 and CDKN2A6,7." (PMID 33741915, 2021). "BAP1 protein belongs to the ubiquitin C-terminal hydrolase subfamily of deubiquitinating enzymes and considered as a key regulator of many cancer-related pathways." (PMID 33761933, 2021). "These class 2 (‘two-hit loss’) drivers include the genes RB1 (3/13 cancer types), NF1 (5/8), NF2 (1/2), PTEN (7/15), and BAP1 (2/6)." (PMID 34862370, 2021). "This suggested that human cancers develop strategies to inhibit ferroptosis by suppressing BAP1 activity." (PMID 33919439, 2021). "Overall, these studies have shown strong supportive data that links BAP1’s functional role in several metabolic pathways, and how dysfunction can promote other pathological issues, including the development of cancer." (PMID 33483476, 2021). "This provides a model in which BAP1 is required to maintain local concentrations of PRC2 and H3K27me3 sufficient for transcriptional regulation while exposing potential therapeutic sensitivities for BAP1 mutant cancers." (PMID 34186021, 2021). "The sisters in generation IV of Family 2 demonstrate a Mendelian inheritance pattern of the two familial cancer predisposition mutations in MSH6 and BAP1 (MSH6: Ex3_9del, pathogenic; BAP1: c.38-1G > A, likely pathogenic)." (PMID 33541411, 2021). "In previous studies, it has been reported that the BAP1 complex consists of important biological roles in development, metabolism, and cancer." (PMID 33483476, 2021). "In line with previous observations in BAP1 knockout mouse ESCs and human cancer cell lines, Western blot analysis showed that H2AK119ub1 levels were markedly increased following BAP1 removal, whereas H2BK120ub1 was unaffected." (PMID 33888563, 2021). "The BAP1 complex has emerged as an ideal therapeutic target for treatments involving developmental/metabolic diseases and human cancers." (PMID 33483476, 2021).
cancer (continued). "The sisters in Family 2 demonstrate a Mendelian inheritance pattern of the two familial cancer predisposition mutations in MSH6 and BAP1." (PMID 33541411, 2021). "Cancer genome sequencing efforts have identified frequently mutated genes in UM, including GNAQ, GNA11, BAP1, SF3B1, and EIF1AX7,25." (PMID 32277165, 2020). "SLC7A11 is an essential BAP1 target in human cancers, and BAP1 represses SLC7A11 expression via reducing H2Aub occupancy on SLC7A11 promoter in a deubiquitinating-dependent manner." (PMID 33425217, 2020). "In vitro studies demonstrated that PVT1 expression drives cancer cell proliferation through promotion of the KLF5/BAP1/beta‐catenin signalling pathway." (PMID 32058674, 2020). "Taken together, these data suggest that in primary UM, TDO2 RNA expression is generally low (compared to other cancers), but the increased TDO2 RNA expression is associated with the poor prognosis markers, BAP1 mutations, and M3." (PMID 32050636, 2020). "Functional studies have emerged as one of the indispensable methods to help classify BAP1 VUS in addition to family cancer history and genetic evidence." (PMID 33240524, 2020). "Germline mutations of the BRCA1 Associated Protein 1 (BAP1), the only gene that has been proposed to influence environmental carcinogenesis, have been indeed reported to increase cancer risk after minimal exposure to asbestos fibers in animal models." (PMID 32059499, 2020). "Our data were consistent with COSMIC in MPM, but were significantly different from COSMIC pan‐cancer data for BAP1 and NF2 (P = 0.008 and P = 0.004, respectively), suggesting specific mutation types for both genes in MPM." (PMID 32083805, 2020). "Several ERGs had the highest mutation frequency repeatedly in many cancer types, namely the KMT2C/D family (seven cancers), ARID1A (five cancers), BAP1 (three cancers), and ATRX (three cancers)." (PMID 32963031, 2020). "Here, we collected RNA-seq data sets from TCGA-BRCA, -UVM, and -COAD projects at Genomic Data Commons Data Portal, and we employed computational techniques to investigate the role of BAP1 in UM and two common cancers, breast and colon." (PMID 30716094, 2019). "It showed that all associations were solely driven by the subset of ERG-negative cancers, while BAP1 staining was unrelated to the analyzed features in ERG-positive cancers." (PMID 31903168, 2019). "Only 2% of AR-negative, but 33% of strongly AR expressing cancers had strong BAP1 expression (p<0.0001)." (PMID 31903168, 2019). "Our analysis showed that the gene expression of BAP1 is significantly different between cancer and control samples for most of the cancer types included in this study." (PMID 31635116, 2019). "We described a cohort of BAP1-TPDS individuals from 22 families in the Netherlands and show a high cancer risk, in concordance with previous reports." (PMID 31382694, 2019). "BAP1 expression was typically up regulated in cancers as compared to adjacent normal prostatic glands." (PMID 31903168, 2019). "Cancer cell fractions of monosomy 3 were close to 1 (mean 0.97), whereas those of BAP1 alterations were lower (mean 0.88), and other passenger mutations on chromosome 3 occurred with much less frequency (mean 0.60)." (PMID 31357599, 2019). "In TCGA (The Cancer Genome Atlas), apart from UM, we identified 29 cancer types with altered BAP1 gene expression." (PMID 31635116, 2019).
cancer (continued). "Although it is known that BAP1 is a tumor suppressor gene important to the development and prognosis of many cancers, especially UM, its role in more common cancers including breast and colon is largely unexplored." (PMID 30716094, 2019). "BAP1 expression was further linked to androgen receptor (AR) expression: Only 2% of AR-negative, but 33% of strongly AR expressing cancers had strong BAP1 expression (p<0.0001)." (PMID 31903168, 2019). "A further analysis in the ERG-negative subset revealed that, for subgroups with identical classical and quantitative Gleason grades, BAP1 expression only had a prognostic impact for Gleason 3+4 carcinomas (p=0,006)." (PMID 31903168, 2019). "BAP1-induced TRAIL resistance extends to other cancer subtypes and is dependent upon functional deubiquitinase and ASXL-binding sites." (PMID 29345617, 2018). "It is well established that the BAP1 region of chromosome 3p is commonly deleted in several cancers including melanomas, breast and lung cancers, among others." (PMID 30477459, 2018). "BAP1 and ASXL1/2 undergo both missense and nonsense mutations in various cancers and exhibit hallmarks of haploinsufficiency, whereby mutations even in a heterozygous form have deleterious effects." (PMID 30258054, 2018). "Serving as tumor suppressor genes in ccRCC, BAP1 and SETD2 mutations were related to worse cancer-specific survival." (PMID 30349421, 2018). "Further in vitro studies are needed to elucidate the functional role of BAP1 down-regulation in cancer cells." (PMID 30395583, 2018). "Inactivating mutations in PBRM1, SETD2, KDM5C and BAP1 tend to be focal in the tumors, so therapies that are designed to exploit the weakness induced by mutation of an individual gene could be problematic since it cannot treat the remaining cancer cells free of that mutation." (PMID 30355451, 2018). "A positive personal and/or family history of BAP1-TPDS tumors was reported for 29 (37%) of the 79 cases that provided information of other cancers in themselves or their families." (PMID 30477459, 2018). "Very recently, we discovered a novel BAP1 cytoplasmic activity that, in concert with its nuclear activities, allows BAP1 to modulate gene–environment interaction and contributes to the high incidence of cancer in BAP1+/− carriers." (PMID 28665402, 2017). "Next-generation sequencing (NGS) (whole genome or exome) has facilitated further discovery of cancer susceptibility genes including RECQL, FANCM, FANCC, XRCC2, POT1, and BAP1 for breast and melanoma, and POLE, POLD1, and NTHL1 for CRC." (PMID 29212164, 2017). "The overall lack of genetic variation in this region is intriguing, particularly when considering the potential role of BAP1 in the tumorigenic process for a number of cancers." (PMID 29088836, 2017). "The increased aerobic glycolysis – ‘Warburg effect’20, 46 – displayed by BAP1+/− cells is frequently observed in cancer cells." (PMID 28665402, 2017). "BAP1 has been identified as a tumor suppressor and as a potential prognostic marker for a number of cancer types." (PMID 27516771, 2016). "BAP1 (BRCA1-associated protein 1; also known as UCHL2) is encoded by a tumour suppressor gene, which is frequently mutated in a range of cancers." (PMID 25833379, 2015). "Here, we investigated cellular localization, enzymatic activity and structural changes for four missense mutants of the catalytic domain of BAP1, which are prevalent in different types of cancer." (PMID 26680512, 2015). "Therefore, loss of BAP1 function due to mutation might lead to cancer progression." (PMID 26680512, 2015). "Genes that were upregulated by demethylation but not methylated included genes that have been described previously as TSGs in other cancer types (e.g. BAP1, IGSF4, RRM2 (Gautam and Bepler (2006)), PMAIP1, claudin-1; and ICAM1;)." (PMID 18195710, 2008). "BAP1 has been reported to serve as an epigenetic regulator in cancer." (PMID 39984455, 2025).